LIG4 (DNA ligase 4)
Description:
DNA ligase involved in DNA non-homologous end joining (NHEJ); required for double-strand break (DSB) repair and V(D)J recombination. Catalyzes the NHEJ ligation step of the broken DNA during DSB repair by resealing the DNA breaks after the gap filling is completed. Joins single-strand breaks in a double-stranded polydeoxynucleotide in an ATP-dependent reaction. LIG4 is mechanistically flexible: it can ligate nicks as well as compatible DNA overhangs alone, while in the presence of XRCC4, it can ligate ends with 2-nucleotides (nt) microhomology and 1-nt gaps. Forms a subcomplex with XRCC4; the LIG4-XRCC4 subcomplex is responsible for the NHEJ ligation step and XRCC4 enhances the joining activity of LIG4. Binding of the LIG4-XRCC4 complex to DNA ends is dependent on the assembly of the DNA-dependent protein kinase complex DNA-PK to these DNA ends. LIG4 regulates nuclear localization of XRCC4.
Synonyms: LIG4S
Tractability: Small molecule: a structure with a bound ligand is known. PROTAC: ubiquitination databases record sites on it; its protein half-life has been measured; a small molecule that binds it is known.
Target class: Enzyme; Ligase
Gene: Protein-coding gene on chromosome 13 (108,207,439 to 108,218,368, reverse strand). Ensembl gene ENSG00000174405.
Subcellular location: Nucleus
Subcellular location (Human Protein Atlas): Nucleoplasm; Vesicles
Pathways (Reactome):
DNA Repair: Nonhomologous End-Joining (NHEJ)
Disease: 2-LTR circle formation
Gene Ontology:
Molecular function: DNA binding; DNA ligase (ATP) activity; DNA ligase activity; ligase activity; magnesium ion binding; protein binding; ATP binding
Biological process: base-excision repair; cellular response to ionizing radiation; double-strand break repair; double-strand break repair via classical nonhomologous end joining; double-strand break repair via nonhomologous end joining; nucleotide-excision repair, DNA gap filling; positive regulation of chromosome organization; response to X-ray; single strand break repair; V(D)J recombination; cell population proliferation; central nervous system development; chromosome organization; establishment of integrated proviral latency; immunoglobulin V(D)J recombination; in utero embryonic development; isotype switching; negative regulation of neuron apoptotic process; neuron apoptotic process; positive regulation of fibroblast proliferation; positive regulation of neurogenesis; pro-B cell differentiation; response to gamma radiation; somatic stem cell population maintenance; T cell differentiation in thymus; and 5 more
Cellular component: condensed chromosome; DNA ligase IV complex; DNA-dependent protein kinase-DNA ligase 4 complex; nonhomologous end joining complex; nucleoplasm; nucleus; chromosome, telomeric region
Genetic constraint (gnomAD): Loss-of-function variants: 16 observed, 23.3 expected, observed/expected ratio (o/e) 0.69, 90% interval 0.46 to 1.04. The upper end of that interval is the gene's LOEUF score, 1.04, which puts it in group 4 of 6, group 1 being the genes least tolerant of losing a copy. Missense variants: 1,023 observed, 1,142.9 expected, observed/expected ratio (o/e) 0.9, 90% interval 0.85 to 0.94. Synonymous variants: 361 observed, 377.4 expected, observed/expected ratio (o/e) 0.96, 90% interval 0.88 to 1.04.
Gene-disease validity (ClinGen):
ClinGen rates the evidence that LIG4 causes each of these diseases.
DNA ligase IV deficiency (autosomal recessive): Definitive. LIG4 syndrome is a hereditary disorder associated with impaired DNA double-strand break repair mechanisms and characterized by microcephaly, unusual facial features, growth and developmental delay, skin anomalies, and pancytopenia, which is associated with combined immunodeficiency (CID).
Homologues: Orthologues: chimpanzee LIG4 (99% identical), macaque LIG4 (97% identical), rabbit LIG4 (91% identical), dog LIG4 (91% identical), pig LIG4 (89% identical), guinea pig LIG4 (88% identical), mouse Lig4 (87% identical), rat Lig4 (86% identical), tropical clawed frog lig4 (73% identical), zebrafish lig4 (64% identical), Drosophila melanogaster DNAlig4 (31% identical), Caenorhabditis elegans lig-4 (19% identical). Paralogues in human: LIG3 (18% identical), LIG1 (17% identical).
Diseases named in the same sentence as LIG4 in open-access papers:
LIG4 is named in the same sentence as 168 diseases in open-access papers, as found by Europe PMC text mining. Sharing a sentence is not in itself a finding about the gene and the disease. The quoted sentences say what the papers report.
Immunodeficiency (34 papers, 2003 to 2026). Failure of the immune system to protect the body adequately from infection, due to the absence or insufficiency of some component process or substance. "LIG4 deficiency typically presents with congenital microcephaly, atypical facial features, growth failure, developmental delay, combined immunodeficiency, sensitivity to ionizing radiation, and increased susceptibility to malignancy." (PMID 40093007, 2025). "DNA ligase IV (LIG4) deficiency, also known as LIG4 syndrome, is an exceptionally rare primary immune deficiency." (PMID 39698004, 2024). "In our cohort of patients with immunodeficiency/immune dysregulation, we identified 2 additional unrelated patients (P3 and P4) carrying another functionally, so far unstudied, monoallelic LIG4 mutation encoding p.A842D (A and Table E2)." (PMID 37004747, 2023). "Biallelic mutations in LIG4 encoding DNA-ligase 4 cause a rare immunodeficiency syndrome manifesting as infant-onset life-threatening and/or opportunistic infections, skeletal malformations, radiosensitivity and neoplasia." (PMID 37004747, 2023). "While mutation in LIG4 can cause autosomal recessive diseases of immune deficiency, growth failure, sensitive to ionizing radiation, and cancer, only 36 cases of diseases caused by LIG4 mutation had been reported so far." (PMID 35595529, 2022). "This syndrome is caused by biallelic pathogenic variants in the LIG4 gene, which cause DNA damage repair disorders, mainly manifesting as severe immunodeficiency." (PMID 36221079, 2022). "Mutations in the LIG4 gene can not only lead to abnormal development of immune defects but also cause severe combined immunodeficiency disease in normal individuals." (PMID 36312587, 2022). "As such, LIG4 deficiency has a broad-spectrum phenotype that includes immunodeficiency, microcephaly, growth failure, facial dysmorphism, malignancy predisposition, and cellular sensitivity to ionizing radiation." (PMID 34630384, 2021). "Human LIG4 deficiency also causes immunodeficiency but here it is due the role of LIG4 in immunoglobulin gene rearrangement as well as a predisposition to cancer." (PMID 34373746, 2021). "According to the clinical manifestations of microcephaly, immune deficiency, and autosomal recessive inheritance pattern, LIG4 was finally identified as the sole pathogenic gene." (PMID 34630384, 2021). "Due to combined immunodeficiency, approximately three quarters of LIG4 deficiency patients suffer from recurrent infections, with varying degrees of severity." (PMID 34630384, 2021). "Disrupted V(D)J recombination in DNA ligase 4 deficiency causes severe combined immunodeficiency, Omenn syndrome, and combined immunodeficiency." (PMID 32010653, 2019). "Patients with hypomorphic mutations in LIG4 present with a range of phenotypes, from normal to severe combined immunodeficiency." (PMID 27717373, 2016). "For instance, the LIG4 syndrome (OMIM #606593), caused by mutations in LIG4, is characterized by immunodeficiency, development and growth delay, unusual facial features, and microcephaly." (PMID 25872942, 2015). "Only 16 cases with mutations in LIG4 have been described to date with phenotypes varying from malignancy in developmentally normal individuals, to severe combined immunodeficiency and early mortality." (PMID 24123394, 2014). "Such growth failure is therefore sufficient to consider a diagnosis of LIG4 deficiency and early recognition of such cases is important as bone marrow failure, immunodeficiency, and sometimes malignancy are long term sequelae of this disorder." (PMID 24123394, 2014). "Impairment of class switch and of V(D)J recombination therefore explain the immunodeficiency and proneness to multiple myeloma and lymphoma observed in LIG4-deficient patients." (PMID 17224058, 2007).
Immunodeficiency (continued). "The ATP-dependent DNA ligase 4 is required for NHEJ and V(D)J recombination, and LIG4 deficiency syndrome, caused by rare LIG4 gene mutations, is manifested via increased radiosensitivity, neurological abnormalities, immunodeficiency and predisposition to cancer." (PMID 37894339, 2023). "This study explored whether monoallelic LIG4 missense mutations may underlie immunodeficiency and autoimmunity with autosomal dominant inheritance." (PMID 37004747, 2023). "When Vα7.2+ TCR frequencies and T-cell bleomycin-induced cell death rates were correlated, 2-dimensional plotting resulted in a distinct segregation of LIG4-mutated patients P1, P3, and P4 with healthy control and also with unrelated patients who had immune disease." (PMID 37004747, 2023). "Recently, germline mutations in LIG4 have been suggested to predispose to diffuse large B-cell lymphomas and to sensitize cell to ionizing radiation, causing immunodeficiency and delay in growth and development in homozygous or compound heterozygous carriers (OMIM#606593)." (PMID 30262796, 2018). "This may be due to the accumulation of DNA-DSB, and therefore progressive apoptosis, in haematopoietic stem cells of LIG4 patients causing progressive immunodeficiency as lymphocytogenesis reduces over time." (PMID 27717373, 2016). "Altogether, the genetic diagnosis of LIG4 deficiency, the history of recurrent infections and the available data on the patient’s immunological status pointed to a condition of immunodeficiency, whose degree, however, cannot be fully ascertained due to the unfortunate passing of the patient." (PMID 27855655, 2016). "The majority of published patients with LIG4 mutations had significant clinical immunodeficiency, including a novel severe combined immunodeficiency (SCID) presentation requiring bone marrow transplant, although this might reflect a reporting bias." (PMID 24892279, 2014). "LIG4-deficient patients are characterized by microcephaly, growth retardation starting in utero, distinctive facial appearance ("bird-like face"), developmental delay, immunodeficiency, pancytopenia, and pronounced clinical and cellular radiosensitivity." (PMID 17224058, 2007). "DNA ligase 4 deficiency, a rare autosomal recessive disorder, is characterized by microcephaly, abnormal dysmorphic (beak-like nose, prominent mid-face, receding forehead, and micrognathia) facial features, combined immunodeficiency, and sensitivity to ionizing radiation." (PMID 32010653, 2019). "Similar to LIG4 and XLF/Cernunnos syndromes, besides marked microcephaly, “bird-like” facial features, developmental delay, immunodeficiency, radiosensitivity, and predisposition to cancer are present." (PMID 37881689, 2023). "This case suggests that LIG4 dificiency can manifest not only as immunodeficiency but also with increased serum IgG levels and pancytopenia, which constitutes an additional clinical phenotype." (PMID 36221079, 2022). "Microcephaly and immunodeficiency are common to DNA ligase IV deficiency (LIG4 syndrome) and severe combined immunodeficiency with microcephaly, growth retardation, and sensitivity to ionizing radiation due to NHEJ1 deficiency (NHEJ1 syndrome)." (PMID 22373003, 2012). "The relatively mild degree of immunodeficiency observed in our patient agrees with the notion of residual LIG4 function as prerequisite for viability." (PMID 17224058, 2007). "The clinical presentation of LIG4 deficiency can range from severe combined immunodeficiency to malignancy without overt immunodeficiency." (PMID 39859044, 2025). "We have documented immunodeficiency, lymphoproliferation, and autoimmunity in the patients analyzed here, including unique complications not yet documented in association with LIG4 deficiency." (PMID 37004747, 2023). "Mutations in LIG4 are characterized by non-progressive microcephaly accompanied by immunodeficiency with or without neurodevelopmental delay." (PMID 37881689, 2023).
Immunodeficiency (continued). "It is classified as a severe immunodeficiency, and our patients mainly present severe immunodeficiency for loss of LIG4 function, whereas P14 had no history of recurrent or severe infection; the only manifestation was cytopenia." (PMID 34630384, 2021). "This Turkish patient, without overt immunodeficiency, developed acute T cell lymphoblastic leukemia at age 14 and was recognized as LIG4 deficient because of an over-response to radiotherapy." (PMID 27855655, 2016). "Mutations in ARTEMIS, LIG4 and XLF genes are known to cause radiosensitive immune deficiency." (PMID 24636752, 2014). "Therefore, LIG4 patients manifest as (severe) combined immunodeficiency." (PMID 32471509, 2020). "DNA ligase IV deficiency (OMIM 606593) or LIG4 syndrome (ORPHA99812), also known as Ligase 4 syndrome, is a rare autosomal recessive disorder characterised by microcephaly, abnormal facial features, sensitivity to ionizing radiation and combined immunodeficiency." (PMID 27717373, 2016). "Similar observations have been performed in cells derived from a patient with hypomorphic mutations in LIG4 that led to pronounced radiosensitivity but did not cause any major immune dysfunction, indicating that defects of DSBs repair are not necessarily associated with immune dysfunction." (PMID 25872942, 2015). "Microcephaly and immunodeficiency are common features in NBS, LIG4 and NHEJ1 syndrome." (PMID 22373003, 2012). "Interestingly, given that XRCC4 is required to stabilise LIG4, it is surprising that to date, none of the patients described exhibit clinical immunodeficiency, despite the marked DNA-DSB repair defect." (PMID 27717373, 2016).
glioblastoma (23 papers, 2010 to 2025). The most malignant astrocytic tumor (WHO grade IV). "When used alone, only TMZ had a significant influence on long-term clonogenic efficiency whereas BMN673 + TMZ were able to almost completely abrogate clonogenic ability of LIG4-deficient glioblastoma cells." (PMID 30627327, 2018). "We postulate that D-NHEJ deficiency resulting from downregulation of LIG4 could be synthetically lethal with B-NHEJ deficiency induced by PARPi in glioblastoma cells exposed to TMZ-induced DNA damage." (PMID 30627327, 2018). "However, whether HDAC inhibitors could sensitize LIG4-deficient glioblastoma to PARPi and TMZ remains to be investigated." (PMID 37763083, 2023). "Elevated expression of LIG4 resulted in resistance of H7 glioblastoma primary cell line to BMN673 + TMZ." (PMID 30627327, 2018). "To examine the potential therapeutic aspect we generated primary glioblastoma cells with downregulated LIG4 when compared to normal human astrocytes." (PMID 30627327, 2018). "In glioblastoma, loss of BRCA2, LIG4, or XRCC4 was associated with more frequent occurrence of complex genome rearrangements." (PMID 30420702, 2018). "Analysis of available mRNA gene expression databases revealed cohorts of glioblastomas displaying lower expression of LIG4." (PMID 30627327, 2018). "Downregulation of LIG4 in glioblastoma cells was directly responsible for enhanced sensitivity to BNM673 as restoration of LIG4 expression resulted in resistance to the treatment." (PMID 30627327, 2018). "Significant changes in the mRNA expression profile of LIG4 was found between glioblastoma cell lines and NHA." (PMID 30627327, 2018). "Additionally, research on glioblastoma cohorts has also shown reduced expression of LIG4, but the specific mechanisms responsible for this reduced expression have not been identified." (PMID 37763083, 2023). "This suggests that glioblastoma cells with reduced LIG4 expression may display increased sensitivity to PARPi when exposed to TMZ-induced DNA damage, potentially leading to a selective targeting of these cancer cells." (PMID 37763083, 2023). "Moreover, transcriptome analysis by microarrays detected downregulation of at least one member of D-NHEJ pathway (including LIG4) in 191 glioblastomas manifesting the proneural, proliferative, proliferative-mesenchymal and mesenchymal phenotypes." (PMID 30627327, 2018). "Inhibition of ATR by AZD-6738 resulted in robust and dose-dependent radiosensitization of glioblastoma cells, whereas LIG4 inhibition by L189 had no noticeable impact." (PMID 35440003, 2022). "PARPi BMN673 in combination with alkylating agent TMZ was effective against patient-derived glioblastoma cells displaying downregulation of LIG4 but not against normal human astrocytes." (PMID 30627327, 2018). "LIG4 downregulation resulting in low effectiveness of DNA-PK–mediated non-homologous end-joining (D-NHEJ), which in combination with BMN673 and TMZ resulted in accumulation of lethal DSBs and specific eradication of glioblastoma cells." (PMID 30627327, 2018). "In our study, we observed that PARP inhibitor (BMN673) was able to specifically sensitize DNA ligase 4 (LIG4)-deprived glioblastoma cells to TMZ while normal astrocytes were not affected." (PMID 30627327, 2018).